WNT1 (Wnt family member 1)
Diseases named in the same sentence as WNT1 in open-access papers (continued):
Sharing a sentence is not in itself a finding about the gene and the disease.
osteosarcoma (6 papers, 2005 to 2025). A usually aggressive malignant bone-forming mesenchymal neoplasm, predominantly affecting adolescents and young adults. "Osteosarcoma progression is linked to Wnt1 signalling activation, along with elevation of c-myc, matrix metallopeptidases, and cyclin-D1, which are genes associated with cell proliferation." (PMID 39926108, 2025). "Inhibition of Sox9 using siRNA has been shown to reduce the expression levels of Wnt1 and Fzd1, resulting in a significant reduction of osteosarcoma cell proliferation." (PMID 38978960, 2024). "Specifically, the WNT1 gene was deleted in 10 cases of the 20 human osteosarcomas with a deletion frequency of 50%." (PMID 24942472, 2014). "Protein expression of WNT1, β-catenin, c-myc, and cyclin D1 in the Wnt pathway was detected by immunohistochemistry (IHC) in an independent group of 46 osteosarcoma samples." (PMID 24942472, 2014). "Out of the differentially modulated genes, those implicated in stem cell and osteosarcoma biology, such as PPARG, ETS1, WNT1, WNT5B, SOX2, NANOG, POU5F1, nestin, and ALDH were chosen for further analysis." (PMID 22870217, 2012). "Wnt1 overexpression is regulated by SRY (Sex-determining Region Y)-Box (SOX9) in osteosarcoma." (PMID 39926108, 2025). "Additionally, Sox9 is involved in the regulation of the Wnt1 and Fzd1 signaling pathway, which plays a critical role in osteosarcoma cell proliferation." (PMID 38978960, 2024). "After confirmation of the efficacy of monoclonal anti-Wnt-1 antibody treatment in A-204 and SJSA-1 cells, we tested its ability to induce cell death in fresh primary cultures of metastatic osteosarcoma that has activated Wnt-1/β-catenin signaling (Cases 3 and 6)." (PMID 15913453, 2005). "WNT1 protein expression was detected in 69.6% (32/46) of the osteosarcomas, however no β-catenin protein expression was observed in the nucleus." (PMID 24942472, 2014). "While WNT1 protein expression was detected by IHC in 69.6% (32/46) of the osteosarcomas, no β-catenin protein was detected in the nucleus." (PMID 24942472, 2014).
Parkinson disease (6 papers, 2011 to 2025). A progressive degenerative disorder of the central nervous system characterized by loss of dopamine producing neurons in the substantia nigra and the presence of Lewy bodies in the substantia nigra and locus coeruleus. "Additionally, upregulation of Wnt1 and β-catenin and attenuation of inducible nitric oxide synthase (iNOS) expression can be associated with neuroprotection in a mouse model of Parkinson’s disease." (PMID 34502498, 2021). "Interestingly, in the MPTP mouse model of Parkinson's disease, previous studies documented the early up-regulation of astrocytic Wnt1 in the ventral midbrain of degenerating substantia nigra neurons as a self-repair intersystem neuroprotective crosstalk 47-50." (PMID 40860154, 2025).
head and neck squamous cell carcinoma (5 papers, 2005 to 2024). A squamous cell carcinoma that arises from any of the following anatomic sites: lip and oral cavity, nasal cavity, paranasal sinuses, pharynx, larynx, and salivary glands. "Among these inhibitors, Wnt974 (LGK974) particularly noteworthy for its demonstrated efficacy in various tumor models including mouse mammary tumor virus-Wnt-1 (MMTV-Wnt1) mouse model and models of human head and neck squamous cell carcinoma." (PMID 38886806, 2024). "Treatment with antibodies against Wnt-1 and Wnt-10b also inhibited proliferation and induced apoptosis in head and neck squamous cell carcinoma (HNSCC) cells." (PMID 19778454, 2009). "Recently, it has been reported that a polyclonal anti-Wnt-1 antibody can downregulate β-catenin/TCF activity and induce apoptosis in head and neck squamous cell carcinoma." (PMID 15913453, 2005).
idiopathic pulmonary fibrosis (5 papers, 2011 to 2024). Idiopathic pulmonary fibrosis (IPF) is a nonneoplastic pulmonary disease that is characterized by the formation of scar tissue within the lungs in the absence of any known cause. "Overexpression of Wnt1 and Wnt10b proteins has been observed in human samples from SS, idiopathic pulmonary fibrosis (IPF), and liver cirrhosis." (PMID 34685439, 2021). "Konigshoff and colleagues confirmed the up-regulation of WNT1, WNT7B and WNT10B, FZD2, FZD3, β-catenin, and LEF1 expression in the lungs of individuals with idiopathic pulmonary fibrosis compared to transplant donor lung." (PMID 21490961, 2011). "Wnt-1 and Wnt-10b were noted to be overexpressed, whereas DKK1 was decreased, which led to the increased nuclear accumulation of β-catenin observed in human tissue samples from systemic scleroderma (SSc), idiopathic pulmonary fibrosis (IPF), and liver cirrhosis." (PMID 34439762, 2021).
mesothelioma (5 papers, 2007 to 2021). A usually malignant and aggressive neoplasm of the mesothelium which is often associated with exposure to asbestos. "A similar dependence on a non-canonical WNT signal was observed in β-catenin-deficient mesothelioma cells, in which siRNAs against WNT1 and DVL induced apoptosis in a JNK (c-jun N-terminal kinase)-dependent manner." (PMID 17897439, 2007). "MM cell cultures expressed high mRNA levels of the mesothelioma markers mesothelin (MSLN), calretinin (CALB2), the WNT1 antagonist DKK1 and the stem cell marker BMI-1." (PMID 20175889, 2010).
craniosynostosis (4 papers, 2012 to 2026). Craniosynostosis is defined as the premature fusion of one or more cranial sutures leading to secondary distortion of skull shape resulting in skull deformities with a variable presentation. "To determine whether a similar cell mixing was the cause of the craniosynostosis in the Gdf6−/− embryos, we visualized the suture boundary using the Wnt1-Cre and R26R transgenic lines, which together stably label derivates of the neural crest, including the frontal bone." (PMID 22693558, 2012). "The scaffold's ability to reconstitute an engineered skeletal stem cell niche and facilitate the functional recovery of the craniosynostosis phenotype is validated in a caBmpr1a; Wnt1-Cre murine model of midline craniosynostosis, the most common nonsyndromic clinical presentation in humans." (PMID 42209469, 2026). "Interestingly, Wnt1-cre;Gsαf/f mutants show round face, shortened snout, hypertelorism and craniosynostosis, these phenotypes are highly similar to the clinical phenotypes observed in GNAS mutations diseases." (PMID 26859889, 2016).
endometrial cancer (4 papers, 2021 to 2025). Primary or metastatic malignant neoplasm involving the endometrium (mucous membrane that lines the endometrial cavity). "Membranous WNT-1 was negatively associated, whereas cytoplasmic WNT-1 and nuclear mTOR were positively associated with higher grading of endometrial cancer." (PMID 37176048, 2023). "The secondary aims were to assess the association of subcellular WNT-1 and mTOR levels with the clinical course of endometrial cancer." (PMID 37176048, 2023). "Our results suggest that a lower WNT-1 level in the membrane was negatively associated with higher-grade endometrial cancer." (PMID 37176048, 2023). "Our current research suggested that the WNT-1 and mTOR pathways may be potential biomarkers of high-risk endometrial cancer." (PMID 37176048, 2023). "First, we provided novel insight into WNT-1 and mTOR levels in different cellular compartments in endometrial cancer." (PMID 37176048, 2023). "Among WNT proteins, WNT-1 is one of the less investigated factors in endometrial cancer, which makes it a good candidate for further research." (PMID 37176048, 2023). "In our studies, we focused on WNT-1 because it was one of the less investigated WNT proteins in endometrial cancer." (PMID 37176048, 2023). "WNT-1 and mTOR levels in the plasma membrane, nucleus, and cytoplasm were evaluated using immunohistochemical staining in a group of 64 patients with endometrial cancer of grades 1–3 and FIGO stages I–IV." (PMID 37176048, 2023). "The primary aim of this study was to assess the levels of the WNT-1 and mTOR proteins in different cellular compartments of endometrial cancer cells." (PMID 37176048, 2023). "E2 and P4 treatment of human endometrial cancer cell lines can induce the expression of miR-152, and miR-152 prevents the G1/S transition of cell cycle and inhibits cell proliferation by down-regulating the expression of WnT-1 (Wnt Family Member 1)." (PMID 40838210, 2025). "Therefore, the aim of our study was to assess the impact of subcellular WNT-1 and mTOR levels on the clinical course of endometrial cancer." (PMID 37176048, 2023). "By using miRNA mimics and inhibitors, it was proved that miR-152 can block G1/S conversion in endometrial epithelial cells (EEC) and inhibit cell proliferation by targeting WNT-1 in endometrial cancer cells, suggesting that miR-152 is a potential anticancer miRNA in endometrial cancer." (PMID 34122542, 2021). "To conclude, our findings suggest that WNT-1 levels in the membrane may be used to rule out high-risk neoplasms, whereas cytoplasmic WNT-1 and nuclear mTOR may be used for confirmation of high-risk endometrial cancer." (PMID 37176048, 2023). "Previous studies on endometrial cancer conducted in Ukrainian and Brazilian populations suggested that WNT-1 was not a good biomarker." (PMID 37176048, 2023). "The novelty of our study is the evaluation of WNT-1 and mTOR levels in non-canonical cellular compartments of endometrial cancer of different grades and stages." (PMID 37176048, 2023).
heart failure (4 papers, 2013 to 2023). Inability of the heart to pump blood at an adequate rate to meet tissue metabolic requirements. "Not surprisingly, downregulation of miR-128 in Axin1 deficient cardiomyocytes had bare effect on reduction of Wnt1/β-catenin, suggesting miR-128 upregulates Wnt1/β-catenin activation and its driven heart failure progression in a Axin1-dependent manner." (PMID 34965835, 2021). "Owing to the embryonic lethality of Alk3 cKO driven by Wnt1-Cre (sudden death caused by heart failure at E12.5 or later), close attention was paid to the condition of all embryos at collection (E12 or younger) to ensure the rigorous heart beat and blood circulation." (PMID 37680190, 2023). "Our study provide evidence to point out that miR-128 deficiency impeded the development of cardiac failure and hypertrophy, which concurrently triggered Wnt1/β-catenin downregulation, implying miR-128 promotes cardiac dysfunction through enhancing Wnt1/β-catenin signaling activation." (PMID 34965835, 2021). "This in turn primes activation of Wnt1/β-catenin and its pathogenic function in heart failure." (PMID 34965835, 2021). "Our study identified a novel co-stimulatory function of miR-128 on Wnt1/β-catenin activation, dedicating to the development of cardiac hypertrophy and heart failure." (PMID 34965835, 2021). "In the present study, using animal model of TAC operation and ISO infusion, we specified a novel pathogenic role of miR-128 in development of cardiac hypertrophy and heart failure, by positive modulating Wnt1/β-catenin signaling pathway." (PMID 34965835, 2021). "Together, these data decisively demonstrated miR-128 mediates the progression of heart failure and the enhancement of Wnt1/β-catenin pathway by downregulatory target on Axin1." (PMID 34965835, 2021). "Collectively, our findings have thus explored a novel pathophysiological role for miR-128 in the stimulation of cardiac hypertrophy and heart failure via direct blemish on the inhibitory activity of Axin1 against Wnt1/β-catenin signaling." (PMID 34965835, 2021). "Our study therefore suggests miR-128 and Wnt1/β-catenin as potential cardiac therapeutic targets and provides a promising therapeutic insight into the treatment of cardiac hypertrophy and heart failure." (PMID 34965835, 2021). "We demonstrate miR-128 and Wnt1/β-catenin are synergistically activated in heart failure, and blockade of miR-128 downregulates Wnt1/β-catenin coupled with reinforced Axin1 expression, leading to ameliorated heart dysfunction." (PMID 34965835, 2021). "Inhibition of miR-128 attenuates, whereas overexpression of miR-128 drives Wnt1/β-catenin activation coupled with hypertrophic aggravation and cardiac dysfunction, suggesting miR-128 acts as a co-activator of Wnt1/β-catenin in cardiac hypertrophy and heart failure." (PMID 34965835, 2021). "Among other extracellular matrix genes, upregulation of periostin, connective tissue growth factor (Ctgf) and WNT1 inducible signaling pathway protein 1 (Wisp1) were most interesting, since their involvement in triggering myocardial fibrosis and heart failure has been previously established." (PMID 24039904, 2013).
Hydrocephalus (4 papers, 2005 to 2024). Hydrocephalus is an active distension of the ventricular system of the brain resulting from inadequate passage of CSF from its point of production within the cerebral ventricles to its point of absorption into the systemic circulation. "Combined, these data indicate that the hydrocephalus phenotype of Pax3flox/flox/Wnt1-Cre mice was caused by defects within the function and structure of the cerebrospinal fluid drainage system beginning in utero." (PMID 26949601, 2016). "Together, these results indicate that stenosis of the posterior segment of the third ventricle and attendant aqueduct defects, along with secondary abnormalities in the superior sagittal sinus, underlie the congenital hydrocephalus in Pax3flox/flox/Wnt1-Cre mutants." (PMID 26949601, 2016). "Soon after birth, P1 Pax3flox/flox/Wnt1-Cre pups displayed mildly enlarged heads, which became domed by P6 onwards, a sign of hydrocephalus." (PMID 26949601, 2016). "As Pax3flox/flox/Pax7−Cre mutants exhibit hydrocephalus similar to Pax3flox/flox/Wnt1-Cre mutants, we examined Pax3 and Pax7 proteins." (PMID 26949601, 2016). "Phenotyping revealed 100% (n = 50/50) of Pax3flox/flox/Wnt1-Cre mutants exhibit an early hydrocephalus phenotype." (PMID 26949601, 2016). "Significantly, all Pax3flox/flox/Wnt1-Cre mutants exhibited an early hydrocephalus phenotype." (PMID 26949601, 2016). "G9a inactivation in neural crest cells using Wnt1-Cre or Sox9-Cre altered proliferation and differentiation of cranial bone cells and decreased ossification of the frontal bones, but did not cause hydrocephalus." (PMID 37470706, 2023). "Notch2 affects Wnt-1 expression, and in mouse the Wnt sw/sw mutant has defective SCO development and hydrocephalus." (PMID 15953386, 2005). "Based on observations of the expression of Wnt1/Wnt3a mRNA and protein levels in IVH rats treated with DFX, some scholars speculated that iron might promote the subarachnoid fibrosis and hydrocephalus after IVH by activation of the Wnt signaling pathway." (PMID 37208490, 2024). "Unexpectedly, we also observed that the remaining Pax3Δ5/f/Wnt1-Cre neonates that did not exhibit a cranial neural tube closure defect developed early-onset hydrocephalus." (PMID 26949601, 2016). "Pathogenesis of Pax3+/Δ5/Pax7+/Δ2 mutant hydrocephalus is grossly and anatomically indistinguishable from that observed in Pax3flox/flox; Wnt1-Cre and Pax3flox/flox/Pax7−Cre mutants." (PMID 26949601, 2016).
metastatic tumor (4 papers, 2015 to 2022). "This assay revealed that WNT1 hypermethylation was present not only in the cfDNA but also in the paired primary and/or metastatic tumor samples of the LBBC patients analyzed." (PMID 36393855, 2022). "Here, we developed a GEMM of metastatic TNBC driven by Prune-1 (MMTV–Prune-1/Wnt1) as a useful resource for preclinical studies to determine the efficacy of immunotherapeutic agents for treatment of established metastatic disease." (PMID 33426510, 2021). "We found that metastatic colonization of the lungs was significantly reduced in the Wnt1 shRNA-transfected groups compared with that in the control shRNA-infected groups in both metastatic tumor models." (PMID 26202299, 2015). "In the subgroup analysis of the 10 cases of SqCCs, the expression of Wnt1 was preserved from the primary to metastatic tumors in 50% (5/10) of cases." (PMID 25574191, 2015). "Metastatic colonization of the lungs was significantly reduced in the Wnt1 shRNA-transfected groups compared with the control shRNA-transfected groups in both metastatic tumor models." (PMID 26202299, 2015). "Alterations in β-catenin expression between the primary and metastatic tumors in the cases of SqCC were accompanied by Wnt1 overexpression but not a loss of E-cadherin expression." (PMID 25574191, 2015). "Among the nine cases of ADC that acquired β-catenin alterations in the metastatic tumors, six cases (66.7%) were accompanied by a reduction in E-cadherin expression, and there was only one case (11.1%) in which Wnt1 overexpression was detected in the metastatic tumor." (PMID 25574191, 2015). "Of note, we also found that the promoter hypermethylation of WNT1 was present not only in cfDNA of LBBC patients but also in their primary and/or metastatic tumors." (PMID 36393855, 2022). "To verify that the hypermethylation of WNT1 found in cfDNA (cg27196808) was also present in the tumor tissues of patients with LBBC, we assessed its methylation status by ddPCR in the available matched primary and/or metastatic tumor tissue samples (n = 4) of our cohort." (PMID 36393855, 2022).
myocardial infarction (4 papers, 2018 to 2025). Gross necrosis of the myocardium, as a result of interruption of the blood supply to the area, as in coronary thrombosis. "After myocardial infarction (MI), cardiac fibroblasts respond to Wnt1 in an autocrine fashion to induce proliferation and fibrogenic genes expression." (PMID 29564334, 2018). "Supporting the idea that increased LRP6/β-catenin due to aggressive mechanical stimulation were associated with cardiomyopathy, the result from immunohistochemistry of isoproterenol-(ISO) induced myocardial infarction animal model showed increased Wnt1 expression compared to that control rat." (PMID 30400259, 2018).
renal cell carcinoma (4 papers, 2019 to 2023). "The results showed that in addition to Wnt1 and Wnt2b, PORCN and other related genes have varying degrees of mutation in renal cell carcinoma, which may mean that PORCN and its related genes will play an important role in renal cell carcinoma." (PMID 32104684, 2020).
Alzheimer disease (3 papers, 2012 to 2024). A progressive, neurodegenerative disease characterized by loss of function and death of nerve cells in several areas of the brain leading to loss of cognitive function such as memory and language. "These categories include WNT (WNT1, WNT3A, WNT6, AXIN2, TNF2, MMP7), Alzheimer disease presenilin (WNT1, WNT3A, WNT6, MMP7), cadherin (WNT1, WNT3A, WNT6) and Notch (LFNG, HES1) signaling pathways." (PMID 38928376, 2024). "Furthermore, identification of microglial cytoprotective pathways for entities such as EPO and Wnt1 may synergistically enhance the development of treatments for Alzheimer's disease." (PMID 22388478, 2012). "In addition, the potential protective capacity of EPO and Wnt1 during Alzheimer’s disease may be linked to the ability of EPO and Wnt1 to govern Bad, Bcl-xL, and caspase activity and increase microglial cell survival during Aβ toxicity." (PMID 23109841, 2012).